MYC (MYC proto-oncogene, bHLH transcription factor)
Diseases named in the same sentence as MYC in open-access papers (continued):
Sharing a sentence is not in itself a finding about the gene and the disease.
lymphoma (continued). "A unique group among high-grade lymphomas, characterized by specific gene rearrangements, these lymphomas carry translocations in MYC together with one, or both, of the anti-apoptotic proto-oncogenes, BCL2 and BCL6." (PMID 37958379, 2023). "The percentage of patients with high-grade lymphoma with gene rearrangements in MYC and BCL2, BCL6, or both was similar." (PMID 37760639, 2023). "Proline dehydrogenase (POX/PRODH) participates in the first step of proline catabolism and is considered a mitochondrial tumor suppressor in MYC-driven lymphoma." (PMID 36982568, 2023). "Further characterisation of high-grade B-cell lymphoma achieved by next-generation sequencing, and mutations of MYC and BCL2 and/or BCL6 genes (“double-hit”-DHIT or “triple-hit”-THIT lymphoma) have been associated in various studies with a worse prognosis." (PMID 37240953, 2023). "RNA-seq of the Eμ-Myc transgenic mouse model of Burkitt lymphoma and the EμSRα-tTA/tet-O-MYC model of T-ALL highlighted changes to the expression of several glycogenes upon MYC-driven leukemia and lymphoma development." (PMID 36897988, 2023). "The reason for this is that aggressive lymphomas with a MYC/BCL2 double hit form a homogeneous group with respect to GEPs and the mutational profile, whereas MYC/BCL6 DH lymphomas are heterogeneous in nature." (PMID 37190213, 2023). "Since it is known that alteration of MYC alone cannot induce a lymphoma and rely on other genetic alterations, DDX3X is a good candidate to investigate." (PMID 37035206, 2023). "In contrast, the EZB-MYC+ subtype, which is associated with concurrent MYC and BCL2 rearrangements (so-called “double-hit” lymphomas [DHL]), exhibited a relatively lower GC TFH signature." (PMID 36765793, 2023). "Inhibition of autophagy with chloroquine enhanced the ability of tumor cells to undergo apoptosis in the MYC-induced model of lymphoma, and this protective autophagy ability is also reflected in our results." (PMID 36691066, 2023). "In Eμ-MYC transgenic B lymphoid cells the loss of TFAP4 dysregulates differentiation resulting in expansion of the rapidly proliferating pre-B cell pool that transforms into fully malignant c-MYC driven lymphoma." (PMID 36894688, 2023). "Along those lines, we and others identified inhibition of the mitochondrial ribosome with the antibiotic tigecycline as a therapeutically viable strategy against MYC‐driven lymphoma." (PMID 37158102, 2023). "These two abnormalities, however, are unlikely to be related, because, in line with a recent report, only one of the IgM gammopathy–positive lymphomas studied here had a MYC translocation." (PMID 37566280, 2023). "These sgRNA transduced Eμ-MYC/Cas9 HSPCs were transplanted into lethally irradiated C57BL/6-Ly5.1 recipient mice that were then monitored for lymphoma development." (PMID 36894688, 2023). "Double-hit or Triple-hit lymphoma (DHL/THL) is an uncommon subset of B cell non-Hodgkin lymphoma with recurrent translocations involving MYC/8q24 and BCL2/18q21 and/or BCL6/3q27, according to the 2016 updated WHO classification of lymphoid neoplasias." (PMID 36823603, 2023). "To study the role of AID in MYC-driven lymphomas, we made use of the λ-MYC model, a transgenic mouse model of MYC-driven lymphomagenesis where a translocated MYC gene from a human BL line was placed under the control of λ chain regulatory sequences." (PMID 37809061, 2023). "Regardless of HGBL-NOS or HGBL with MYC, BCL2 and/or BCL6 rearrangements (double/triple-hit lymphoma), the detection of MYC, BCL2 and BCL6 by FISH is necessary for a clear diagnosis." (PMID 37182167, 2023). "This accumulation of pro-B/pre-B cells in the sgTfap4/Eμ-MYC/Cas9 pre-leukaemic recipients is consistent with the immuno-phenotyping of the malignant lymphomas arising in these mice." (PMID 36894688, 2023).
lymphoma (continued). "cannot explain data that haploinsufficiency for Rpl24, which reduces global protein synthesis, abrogates c-MYC-induced lymphoma." (PMID 37035206, 2023). "Aggressive lymphomas with an MYC and BCL6 double hit and either DLBCL or HGBL morphology comprise 5 bis 10% of cases." (PMID 37190213, 2023). "Such MYC-driven lymphomas can be modelled pre-clinically using the Eμ-Myc transgenic mouse model, which recapitulates the immunoglobulin/c-MYC chromosomal translocation characteristic of BL, and results in pre-B/B cell lymphomas with almost 100% incidence." (PMID 36755070, 2023). "Western blot analysis showed that, with one exception, MYC protein was lower in γ-irradiation-induced T lymphomas than in MYC10hom transgenic T lymphomas, but nevertheless still far higher than in a normal thymus." (PMID 36755068, 2023). "MYC upregulation in lymphoma is frequently accompanied by additional translocations leading to the inactivation of the BCL6 repressor and activation of the BCL2 oncoprotein." (PMID 36969025, 2023). "As expected, characteristic translocations of the 3′ end of BCL2 to the IGH locus were detected in all lymphomas, with MYC translocations to various partner loci seen upon transformation to DHL." (PMID 38049665, 2023). "In Eμ-MYC mice, which express transgenicc-MYC in B cells and develop aggressive lymphomas and leukemia, globalCry2 deletion reduces survival and enhances tumor formation." (PMID 37811199, 2023). "Subsequent data described, that some rare cases with 11q gain/loss have simultaneously rearrangement or amplification of MYC and are diagnosed as BL or HGBL,NOS, or even double-hit lymphoma with BCL2 rearrangement." (PMID 37941034, 2023). "For instance, a clinical mTOR inhibitor, blocking mTOR-dependent 4E-BP1 phosphorylation in human lymphomas, confers such synthetic lethality with MYC, demonstrating that MYC can become better druggable by applying this principle." (PMID 36969025, 2023). "Failure of interim PET to predict outcome has also been reported for lymphomas harboring a MYC translocation whose frequency in DLBCL is similar (10–15%) to that of an associated IgM gammopathy." (PMID 37566280, 2023). "Many studies have shown that MYC plays a pivotal role in the occurrence and development of lymphoma." (PMID 37641492, 2023). "Eμ-MYC lymphoma cells are generally dependent on the pro-survival BCL-2 family member MCL-1 for their sustained survival." (PMID 36894688, 2023). "We identified TFAP4 as a potent suppressor of c-MYC driven lymphoma development in a previous genome-wide CRISPR knockout screen in primary cells in vivo." (PMID 36894688, 2023). "Decitabine treatment resulted in prolonged lymphoma-free survival in all T-LBL PDX models, which was associated with downregulation of the oncogenic MYC pathway." (PMID 36765607, 2023). "Changes in lipid profiles provide new biological insights into how MYC regulates cellular metabolism in MYC-induced lymphoma." (PMID 36982568, 2023). "The rapid diagnosis of double/triple-hit lymphomas (DHLs/THLs) involving MYC, BCL2 and/or BCL6 rearrangements is obligatory for optimal patient care." (PMID 37958379, 2023). "Enitociclib intermittent dosing downregulates transcription factors including MYC, providing a therapeutic window for durable responses in patients with MYC+ lymphoma." (PMID 37882668, 2023). "Genetic rearrangements of MYC and BCL2 and lymphoma derived from MYC and BCL2 co-expression have received increasing attention in recent years." (PMID 35198451, 2022). "It is worth mentioning that all the cryptic MYC insertions in lymphomas reported in the literature and in the present study result in the fusion of MYC with IGH." (PMID 35167621, 2022).
lymphoma (continued). "A more simplified algorithmic approach was adopted by the Royal College of Pathologists (UK) as outlined in the 2015 lymphoma dataset, which recommends testing MYC and BCL2 by FISH." (PMID 35626243, 2022). "MYC is a master regulator of cell survival in immune cells, and its overexpression is frequently observed in aggressive forms of lymphoma, such as diffuse large B cell lymphoma (DLBCL) and PCNSL." (PMID 36226068, 2022). "Aggressive lymphomas appear to have acquired additional oncogenic alterations that cooperate with MYC dysregulation by counteracting its pro-apoptotic function." (PMID 35626262, 2022). "The importance of this goes beyond EBV-driven lymphomas as MYC overexpression was able to induce similar changes in 1C metabolism even when the EBV-encoded viral factor EBNA2 was inactivated." (PMID 36428647, 2022). "One of the non-coding targets is the MYC-repressed microRNA-150 (miR-150), an important tumor suppressor in lymphoma." (PMID 35205272, 2022). "Here, we demonstrated that MYC-dependent lymphomas are extremely sensitive to the highly specific HDAC6 inhibitor M-100." (PMID 36068335, 2022). "A c‐MYC–CD19 regulatory loop, in which CD19 and c‐MYC act synergistically, accelerates B‐cell lymphomagenesis and lymphoma progression." (PMID 35488888, 2022). "MYC is a well-known blood oncogene that is particularly important in lymphomas and has a crucial influence on cell survival and proliferation." (PMID 35456380, 2022). "These lymphomas are often called double-hit lymphomas, or triple-hit lymphomas if there are both Bcl-2 and Bcl-6 rearrangements in addition to the MYC rearrangement." (PMID 36618391, 2022). "Taken together, these data provide evidence that PHGDH is an effective therapeutic target in MYC-driven lymphoma." (PMID 35316216, 2022). "In DHL/THL model, OTX015 (Birabresib) combined with BCL2 antagonist (such as Venetoclax) synergically inhibited the malignant proliferation of DHL/THL cells, supporting the combining use of BETi and BCL2 inhibitors against MYC-driven lymphoma." (PMID 35303910, 2022). "In contrast to healthy ABCs, where PHGDH blockade has a cytostatic effect, inhibition of this enzyme in lymphoma cells induces apoptosis, likely reflecting the impact of MYC overexpression." (PMID 35316216, 2022). "Indeed, MYC-driven lymphoma may be particularly susceptible to serine deprivation, as previous work has demonstrated that the progression of lymphoma in Eμ-Myc mice can be slowed by reducing the availability of extracellular serine and glycine by dietary restriction." (PMID 35316216, 2022). "C-MYC/BCL-2 double-hit lymphoma has been recognized as a chromosomal break involving MYC and BCL-2, which is very rare, representing 3% of all DLBCL cases." (PMID 35875161, 2022). "Here, for the first time, we aimed at evaluating the effect of IBTK on MYC in aggressive lymphoma B cells to elucidate the role of IBTK in B-cell lymphoma progression." (PMID 35216159, 2022). "These so-called “double-hit” or “triple-hit” (DH/TH) lymphomas have been included in the 2016 updated WHO classification in the new category of high-grade B cell lymphoma (HGBL) with rearrangements of MYC and BCL2 and/or BCL6." (PMID 35060000, 2022). "A recent study showed that nonbenzodiazepine BETi, PLX-2853, synergize with venetoclax to induce apoptosis in MYC-driven lymphomas with high BCL2 expression." (PMID 35303910, 2022). "Despite these remaining uncertainties, this report reveals the major regulatory role that the RelA T505 phosphosite has as a regulator of the DNA replication stress response in an in vivo model of MYC driven lymphoma." (PMID 36240065, 2022). "Human MYC-overexpressing lymphoma cells responded to M-100 treatment with a strong induction of apoptosis." (PMID 36068335, 2022). "We also reported that Tigecycline and venetoclax cooperated in killing MYC/BCL2 double‐hit lymphoma cells, and showed synergy against DHL in a preclinical setting." (PMID 34632715, 2022).
lymphoma (continued). "For example, studies in murine Eμ-MYC pro–B-cell leukemia/lymphomas suggested that ATF4 is induced by ER stress and MYC-induced nutrient exhaustion." (PMID 35019856, 2022). "This raised the fundamental question of how these lymphoma cells were still able to survive, given that CHK1 is required in the WT lymphomas to cope with high levels of MYC-induced DNA replication stress." (PMID 36240067, 2022). "CD24 expression was higher in BL than in DLBCL including double‐hit lymphoma, lymphoma with single hit of the MYC gene, and DLBCL, NOS in Hummel's dataset (GSE4475)." (PMID 35289116, 2022). "TRIB3 interacted with MYC to suppress E3 ubiquitin ligase UBE3B-mediated MYC degradation, which induced the enhanced expression of MYC, causing the proliferation of lymphoma cells." (PMID 35668944, 2022). "In summary, our study provides data for the role of the PRMT5/MSI2 axis in regulating the key lymphoma drivers, c-MYC and BCL-2." (PMID 36167829, 2022). "The literature data regarding the cryptic MYC insertions in lymphomas are scarce; only a few incidences of this aberration in BL have been reported." (PMID 35167621, 2022). "Lymphomas with rearrangements of MYC with BCL2 and/or BCL6 are called “double-hit lymphomas”(DHL) or “triple-hit lymphomas”(THL)." (PMID 35498426, 2022). "In animal models, targeted inhibition of PD-1/PD-L1 axis by combining anti-PD-1 antibodies and BET inhibitors has synergistic response in MYC-driven lymphomas." (PMID 35226658, 2022). "Pharmacological inhibition of CDK1 led to selective killing of cells expressing oncogenic levels of MYC and reduced in vivo growth of MYC‐driven lymphomas." (PMID 36214609, 2022). "CDK9 inhibition by dinaciclib appears to be particularly successful in promoting the regression of aggressive MYC-driven lymphomas by selectively inhibiting key MYC targets such as MCL1." (PMID 35408915, 2022). "We tested if PRMT5 and MSI2 inhibitors alone or in combination affected c-MYC mRNA in lymphoma cells." (PMID 36167829, 2022). "Other enzymes in the same pathway were also induced by MYC and one of these, ADSL, was identified through an in vivo RNAi screen as a critical MYC effector in lymphoma." (PMID 36214609, 2022). "CBP/p300 bromodomain inhibition blocks GATA1 and MYC oncogene expression and induces chronic myeloid leukemia and lymphoma cell cycle arrest and growth inhibition." (PMID 35836809, 2022). "Triple expressor lymphoma is a subgroup of non-Hodgkin's lymphomas that exhibits simultaneous overexpression of the MYC, BCL2, and BCL6 genes." (PMID 36505167, 2022). "The c-MYC protein contributes to the apoptotic pathway and the growth of lymphocytes in neoplastic lymphomas, suggesting that c-MYC is a key transcription factor." (PMID 36536747, 2022). "Earlier studies reported that double-hit lymphoma harbored MYC translocations or rearrangement, which led to high expression of MYC." (PMID 35091546, 2022). "First, MYC‐ and OxPhos‐related gene signatures were highly correlated in six distinct DLBCL patient cohorts, and were enriched in MYC‐overexpressing mouse B‐cells and lymphomas." (PMID 34632715, 2022). "MYC has been reported to positively regulate PD-L1 expression in a variety of cancers, including esophageal squamous cell carcinoma, NSCLC, and lymphoma, with evidence indicating that MYC directly regulates the expression of PD-L1 at the transcriptional level." (PMID 35090497, 2022). "The implication of MYC rearrangement in CD24‐expressed lymphoma prompted us to explore the relationship between MYC aberration and CD24 expression in B‐cell lymphoma including Burkitt lymphoma (BL)." (PMID 35289116, 2022). "Deregulated MYC expression is commonly found in lymphoma due to MYC-coding sequence translocation to the vicinity of immunoglobulin enhancers." (PMID 35814434, 2022). "Several articles have reported the correlation between increased MYC expression and resistance to Crizotinib in lung cancer and lymphoma cells." (PMID 35563017, 2022).
lymphoma (continued). "While MYC rearrangements can occur in other forms of lymphoma (they are present in about 10% of DLBCL, for instance), they are always present in BL." (PMID 36158446, 2022). "Lymphomas with chromosomal rearrangements of MYC and BCL2 and/or BCL6 (double- and triple-hit lymphoma, now classified as high-grade lymphoma) are commonly of GCB subtype." (PMID 35305092, 2022). "The λc-MYC mouse model bearing a translocated c-MYC gene from the human BL line IARC-BL60 exhibits aggressive lymphomas with striking similarities to human BL." (PMID 35740961, 2022). "The treatment of JQ1 (a classic inhibitor of BRD4) extended survival in a mouse xenograft model of MYC-driven lymphoma, suggesting that BETi has broad therapeutic potential in DHL that is highly associated with MYC." (PMID 35303910, 2022). "MYC activation occurs more frequently in Moloney murine leukemia virus induced lymphomas in p27 knock-out than in WT tumors." (PMID 35597806, 2022). "One of these drugs, BEZ235 (dactolisib), showed efficacy on preclinical models of MYC‐driven lymphoma, mediated by inhibition of the DNA damage response kinase ATM along with mTOR." (PMID 36214609, 2022). "Double-hit lymphoma is one of the most aggressive and refractory lymphoma subtypes with recurrent genetic abnormalities of MYC and BCL-2 or BCL6 rearrangement, leading to a poor prognosis in the present clinical practice." (PMID 35091546, 2022). "Inactivating MYC is sufficient to induce cancer regression in diverse models of MYC‐driven cancer lymphoma, skin papilloma, and osteosarcoma, a phenomenon known as ‘oncogene addiction’." (PMID 36214609, 2022). "The phenomenon of MYC insertions in lymphoma is known; however, data regarding the occurrence of this abnormality in BL are limited." (PMID 35167621, 2022). "Further analyses reveal that glutamine supports viability through TCA cycle energetics rather than asparagine biosynthesis and that TCA cycle inhibition confers tumour suppression on MYC-driven lymphoma in vivo." (PMID 35945217, 2022). "The vast majority of reports regarding MYC insertions in lymphomas are based on retrospective analyses or isolated cases." (PMID 35167621, 2022). "The other cause is that IGK/MYC and IGL/MYC testing in MYC-negative lymphomas is performed sporadically." (PMID 35167621, 2022). "The breakpoints of the MYC are widely dispersed across the large >1 Mb region, and depend on the lymphoma subtype and translocation partner." (PMID 35167621, 2022). "Recent studies have identified that certain subpopulations of DLBCL and BL contain MYC, Bcl-2 and/or Bcl-6 translocations and were called “double hit” lymphoma (DHL) or “triple hit lymphoma” (THL)." (PMID 33412518, 2021). "Early regulatable models of lymphoma include mouse strains expressing human MYC from tetracycline/doxycycline regulatable promoters which develop T, B and myeloid lineage malignancies that regress upon doxycycline induced repression of MYC expression." (PMID 34484175, 2021). "The same Myc breakpoint region on chromosome 8 is also a recurring hotspot of MYC-IGH fusions in DLBCL lymphomas." (PMID 33802828, 2021). "Pell‐1 cells also retained the c‐MYC rearrangement and immunophenotypic features of primary lymphoma cells." (PMID 34821060, 2021). "Tumor reversion was also observed upon MYC suppression in several malignancies, including T and B cell leukemia and lymphoma, squamous cell, and mesenchymal cancers." (PMID 33958005, 2021). "Mice with either insufficient MYC or reduced ribosome biogenesis have a slower incidence of MYC driven lymphomas, and an inhibitor of RNA polymerase I transcription is in clinical trials in patients with hematological malignancies." (PMID 34885204, 2021). "We would thus expect to observe regulation of genes involved in MYC-induced lymphoma development at 48 h, even though some genes are likely to be indirect targets of MYC." (PMID 34885204, 2021).